INS (insulin)
Diseases named in the same sentence as INS in open-access papers (continued):
Sharing a sentence is not in itself a finding about the gene and the disease.
neuroblastoma (continued). "The nanobody was radiolabelled and in vivo SPECT/CT imaging and biodistribution studies were performed in immunodeficient mice that were either transplanted with DPP6-expressing Kelly neuroblastoma cells or insulin-producing human EndoC-βH1 cells." (PMID 29123178, 2017). "The lead nanobody, 4hD29, was radiolabelled and in vivo SPECT/CT imaging and biodistribution studies were performed in immunodeficient mice transplanted with DPP6-expressing Kelly neuroblastoma cells or insulin-producing human EndoC-βH1 cells." (PMID 29123178, 2017). "A human neuroblastoma cell line stably transfected with the Ob-Rb leptin receptor (SH-SY5Y-ObRb) was treated with insulin (300 nM, 4 h)." (PMID 27677243, 2016). "By contrast, prolonged exposure to insulin, in both human neuroblastoma cells (up to 60 min of treatment), and human neuronal NT2N cells (5 min of treatment), results in a significant decrease in Tau phosphorylation." (PMID 24574966, 2014). "Taken together, these results demonstrate that DEPP is a transcriptional target of FOXO3 and regulated downstream of insulin-signaling in neuroblastoma cells." (PMID 25261981, 2014). "In this work we have investigated the use of engineered Autographa californica multiple nuclear polyhedrosis virus (AcMNPV) as a gene delivery tool to study insulin mediated events in human neuroblastoma SHSY-5Y and hepatic C3A cells." (PMID 17309805, 2007). "We show that adenovirus mediated gene transfer in human neuroblastoma SHSY-5Y and liver C3A cells cause a dose dependent phosphorylation of Akt and that this makes the cells unresponsive to insulin." (PMID 17309805, 2007). "AAH and Humbug are over-expressed in SH-Sy5y neuroblastoma cells, and their mRNAs are regulated by insulin/IGF-1 signaling through Erk MAPK, PI3 kinase-Akt, and Cdk-5, which are known mediators of cell migration." (PMID 17156427, 2006). "In addition, the co-immunoprecipitation of MIDN-Flag with EGR1 was also detected in SH-SY5Y cells, a human neuroblastoma cell line, when treated with insulin (1 μM, 2 h)." (PMID 39264361, 2024). "In this relationship, in differentiated human neuroblastoma cells, SK-N-SH, the insulin treatment concomitant to acute ferrous iron exposure, performed in acidic conditions to promote maximum DMT1 uptake, showed greater neuroprotection from cell death, compared to the control treatment." (PMID 39062570, 2024). "In serum-starved neuroblastoma SH-SY5Y cells, we found that stimulation of the mTORC1 pathway with insulin or serum readdition caused a mobility shift of Unkempt to a higher resolved band, whereas direct inhibition of mTORC1 kinase activity with rapamycin prevented this shift." (PMID 36509146, 2023). "Thus, the antioxidant effects of insulin on the glutamate-induced accumulation of unspecified ROS in differentiated human SH-SY5Y neuroblastoma cells have been previously shown." (PMID 36293449, 2022). "Similarly, overexpression of APP and PS1 in LAN5 neuroblastoma cells treated with metformin was suppressed by insulin." (PMID 35153733, 2021). "Gupta found that metformin could inhibit the increase of AChE activity by 34.9% in insulin-resistant neuroblastoma cells." (PMID 35153733, 2021). "Immunofluorescent staining of N2a neuroblastoma and U87 astrocytoma cells showed that, under basal conditions, FoxO3 primarily resided in the cytoplasm, and this pattern was maintained upon insulin treatment." (PMID 34247441, 2021). "In the current study, we showed that O-GlcNAcylated APP in response to insulin could reduce the localization of APP in lipid rafts using neuroblastoma SH-SY5Y cells expressing APP and BACE1 as well as cultured hippocampal neurons from Sprague Dawley rats." (PMID 34940409, 2021). "Furthermore, increased expression of TRPV1 receptor protein has been demonstrated following long-term administration of IGF-1 and insulin in TRPV1 receptor-expressing neuroblastoma cells." (PMID 32260335, 2020).
neuroblastoma (continued). "Moreover, HT completely reverses the toxic effect produced by amyloid insulin aggregates in neuroblastoma cell lines by fully inhibiting the production of toxic amyloid species." (PMID 32629793, 2020). "Utilizing a combination of our Drosophila models of tauopathy (expressing the 2N4R-Tau) and neuroblastoma cells, we have attempted to decipher the pathways downstream of the insulin signaling cascade that lead to tau hyperphosphorylation, aggregation and autophagic defects." (PMID 31427921, 2019). "DEPP expression is inhibited by insulin-growth signaling in neuroblastoma cells." (PMID 25261981, 2014). "We demonstrated, for the first time to our knowledge, that rebaudioside A and stevioside, the major glycosides in Stevia extracts, are able to enhance glucose uptake in both SH-SY5Y neuroblastoma and HL-60 myeloid leukaemia human cells, the raise being similar to that induced by insulin." (PMID 24327825, 2013). "Interestingly, insulin transiently promotes tau phosphorylation by activating GSK-3β in SH-SY5Y neuroblastoma cells and primary cortical neurons." (PMID 22536436, 2012). "Furthermore, we suggest that this phenomenon can be avoided by using recombinant AcMNPV baculovirus mediated gene transfer when studying insulin signalling in human neuroblastoma or liver cells." (PMID 17309805, 2007). "To determine whether the insulin-induced alteration in the total and phospho-tau levels that we observe in our Drosophila tauopathy models, is conserved in human cells, we next investigated the effect of insulin treatment in neuroblastoma cells." (PMID 31427921, 2019). "SGs increased the activity of the glucose transporter in human leukemia cells HL-60 and human neuroblastoma cells SH-SY5Y, similar to that of insulin action." (PMID 39170696, 2024). "We were extremely curious about this compound’s effect on the α-syn accumulation in primary dopaminergic neurons since in the literature, both insulin and IGF-1R are reported to reduce α-syn toxicity in the neuroblastoma cell lines." (PMID 35454152, 2022). "We observed elevated expression of both PHLPP1 and PHLPP2 in insulin resistant neuronal cells (Neuro-2A, mouse neuroblastoma; SHSY-5Y, human neuroblastoma) as well as in the whole brain lysates of high-fat-diet mediated diabetic mice." (PMID 36376971, 2022). "Here, we investigated the impact of palmitic acid on insulin responsiveness and its potential effects on TLR4 expression and resistin action in human SH-SY5Y neuroblastoma cell line." (PMID 33686181, 2021). "We demonstrate the effects of both acute and chronic insulin treatment, and the impact of inhibiting PI3-Kinase signaling on choline uptake in SH-SY5Y neuroblastoma cells that are transfected to stably express CHT (SY5Y-CHT cells)." (PMID 26161852, 2015). "There are experimental data that insulin-induced reactive oxygen species (ROS) and H2O2 play a role in the activation of insulin signaling in neuroblastomas." (PMID 17919343, 2007). "Initial studies characterized the signaling pathways that are likely to mediate insulin and IGF-1 signaling in SH-Sy5y neuroblastoma cells." (PMID 17156427, 2006). "On the other hand, treatment of neuroblastoma cells with 200 μM PA did not affect cell viability but blocked insulin-induced metabolic activation, inhibited the activation of the insulin/PI3K/Akt pathway, and activated mTOR kinase." (PMID 38786008, 2024). "We investigated the effects of TIR on markers of neuronal growth (CREB and BDNF), apoptosis (BAX/Bcl2 ratio) differentiation (pAkt, MAP2, GAP43, and AGBL4), and insulin resistance (GLUT1, GLUT4, GLUT3 and SORBS1) in a neuroblastoma cell line (SHSY5Y) exposed to normal and high glucose concentration." (PMID 38287296, 2024). "Previously, we have shown α-amylase-dependent changes in insulin secretion in pancreatic β cells, which express GLUT2, thus supporting our notion that at least glucose uptake by GLUT2 may be affected by α-amylase in neuroblastoma cells." (PMID 35924266, 2022).
neuroblastoma (continued). "We used a neuroblastoma PDX model where tumors were dissected into 1-mm3 pieces and cultured in duplicate on a presoaked gelatin sponge in 24-well plates containing 500 μL RPMI 1640 with 10% FBS, antibiotic/antimycotic solution, 0.01 mg/mL hydrocortisone, and 0.01 mg/mL insulin." (PMID 32850011, 2020). "Importantly, changes in TRPV1 receptor gene expression may also contribute to a decrease of TRPV1 receptor agonist-induced smooth muscle contraction since, in neuroblastoma cells, TRPV1 receptor gene transcription has been shown to be insulin-dependent." (PMID 32260335, 2020). "Thus, short insulin treatment (<2–3 min), either in rat primary cortical neurons, or in SH-SY5Y human neuroblastoma cells, leads to a rapid and transient Tau hyperphosphorylation at the AT8 (Ser202/Thr205), AT180 (Thr231), PHF-1 (Ser396/Ser404) and T3P (Ser396) epitopes." (PMID 24574966, 2014). "Therefore, we concluded that STZ induces rather non-specific cytotoxicity to the undifferentiated cells without the development of significant insulin resistance, which might be explained by the high sensitivity of rapidly proliferating neuroblastoma cells to cytotoxic compounds like STZ." (PMID 33616807, 2021). "However, in neuroblastoma cells DEPP-induction by growth factor withdrawal is strongly reduced in the presence of a dominant-negative FOXO mutant suggesting that DEPP regulation by insulin/growth factor signaling almost exclusively relies on FOXO transcription factors." (PMID 25261981, 2014).
hypercortisolemia (57 papers, 2012 to 2026). "While we did not observe an association between cortisol and birth weight, hypercortisolism is expected in pregnancy and contributes to the physiologic maternal insulin resistance that facilitates mobilization of maternal nutrients for fetal growth." (PMID 40787011, 2025). "Because the PNS offspring is vulnerable to stress, this results in hypercortisolemia, which is associated with basal and glucose-induced enhanced insulin secretion." (PMID 39000130, 2024). "Low-grade metabolic acidosis has been associated with hypercortisolism, which decreases insulin sensitivity and increases insulin resistance." (PMID 35565143, 2022). "Modern Ramadan practices in Saudi Arabia are associated with evening hypercortisolism and increased insulin resistance." (PMID 23637777, 2013). "Hypercortisolemia is associated with impaired insulin action." (PMID 39863744, 2025). "As seen in patients with Cushing’s syndrome, increased NC values ​​may be associated with hypercortisolemia and trunk obesity due to decreased insulin sensitivity." (PMID 36402951, 2022). "Moreover, hypercortisolism can cause alterations in body composition with increase in visceral adiposity, increased fasting insulin, and decreased bone mass." (PMID 25386368, 2014). "Disruption of the homeostasis over a long period of time due to stress, leads to metabolic imbalance, insulin resistance, hypercortisolemia –as cortisol is the main stress hormone–, and chronic low-grade inflammation." (PMID 40868462, 2025). "Increased pituitary GH production, decreased cellular glucose absorption, and impaired insulin synthesis are just some of the metabolic consequences of hypercortisolemia." (PMID 40559821, 2025). "In dogs with hypercortisolism and concurrent DM, the median insulin dose increased significantly at t1 (P<0.05) and t2 (P<0.05) during trilostane treatment, compared to t0." (PMID 39535393, 2024). "Despite being quite different conditions, the insulin resistance pattern induced by the diestrus and glucocorticoid excess due to hypercortisolism was shown to be similar." (PMID 38539988, 2024). "Spaying induced diabetic remission for four months in a case report of a poorly responsive-to-insulin-treatment Schnauzer dog with concomitant hypercortisolism and multiple mammary masses." (PMID 38539988, 2024). "Hypercortisolism is considered one of the mechanisms involved in developing MetS by inhibiting insulin action, increasing lipase activity and gluconeogenesis." (PMID 38092828, 2023). "Hypercortisolism is known to impact glucose metabolism through decreased pancreatic secretion of insulin and increased hepatic gluconeogenesis." (PMID 35212862, 2022). "At the metabolic level, the observed increased availability of IRS2, IGFBP2 and, to a lower extent, IRS1 after treatment suggested an elevated sensitivity to insulin in VAT under hypercortisolemia." (PMID 35737302, 2022). "Several studies have also shown the adverse impact of hypercortisolemia on insulin sensitivity, glycemic control and lipid metabolism." (PMID 30796508, 2020). "We have reported that maternal obesity (MO) during ovine pregnancy results in hyperphagia, glucose-insulin dysregulation, increased adiposity, hypercortisolemia and hyperleptinemia in mature offspring subjected to a bout of ad libitum feeding." (PMID 28771488, 2017). "Her initial presentation included rising insulin requirements, followed by overt hypercortisolism." (PMID 42221400, 2026). "Higher androgen concentrations, hypercortisolism and unfavorable body composition may contribute to decreased insulin sensitivity in CAH patients." (PMID 35454339, 2022). "Second, increased activation of the hypothalamic–pituitary–adrenal axis, sympathetic nervous and immune systems in response to stress could lead to hypercortisolemia, increased gluconeogenesis, and reduced insulin secretion." (PMID 29896155, 2018).
hypercortisolemia (continued). "The reasons for a direct relations of age and MetS is that age related processes such as gradual decrease in the basal metabolic rate, stress induced hypercortisolism, hypogonadism, decreased growth hormone secretion, concomitant insulin resistance and abdominal fat deposition." (PMID 30016936, 2018). "Additionally, these patients present mild hypercortisolemia, low serum insulin levels, low insulin-like growth factor 1 (IGF-1) and low total triiodothyronine." (PMID 25201001, 2014). "Reported evidence after 6 weeks of vitamin D3 supplementation in patients with hypercortisolemia had an effect on lipid profile and insulin sensitivity but did not significantly affect baseline body weight (BMI, waist circumference)." (PMID 37762245, 2023). "Soon after initiation of metyrapone treatment, his glucose levels became stable and insulin injections were tapered, and insulin injections and potassium supplementation were no longer required along with the correction of hypercortisolemia." (PMID 35854271, 2022). "The reason could be that the influence of hypercortisolemia on glycemic control was successfully counteracted by higher insulin doses; unfortunately we have no information of their insulin doses." (PMID 25224993, 2014).
hypogonadism (57 papers, 2009 to 2025). A disorder characterized by decreased function of the gonads. "Analyzing the basal hormone secretions and stimulation tests (ACTH test and insulin tolerance test), we diagnosed subsequent panhypopituitarism (secondary hypercorticism, hypothyreosis, hypogonadism, and growth hormone deficiency (GHD) in adults)." (PMID 40686398, 2025). "So, the better insulin regulation can positively impact testosterone production and decrease the risk of metabolic disorder that can lead to hypogonadism." (PMID 40811476, 2025). "Likely contributors include insulin signaling associated with adiposity, permissive thyroid hormone action, local growth-plate paracrine pathways, and, in hypogonadism, delayed epiphyseal closure." (PMID 41464859, 2025). "The data reported indicate that, in the case of testosterone deficiency in IS hypogonadism, glycolysis and glutaminolysis produce energy, probably due to the fact insulin increases ATP and NADH levels and promotes glutaminolysis." (PMID 36361519, 2022). "Replacement therapy in diabetic men with lowered T may improve insulin sensitivity, glycemic control, cardiovascular risk factors, and diabetic complications but long-term influence of T in men with hypogonadism and PD is still unknown." (PMID 27274996, 2016). "Growth hormone deficiency and hypogonadism may contribute to the lower fasting insulin levels and greater insulin sensitivity in PWS compared to “normal” obese individuals." (PMID 26334732, 2015). "Multiple factors contribute to secondary hypogonadism, including inflammatory mediators of low chronic inflammation, such as tumor necrosis factor and interleukin 1; insulin resistance; leptin resistance; and reduced kisspeptin secretion." (PMID 37479795, 2023). "Currently, the most widely accepted mechanism of diabesity-related hypogonadism is that insulin and leptin resistance diminishes the stimulatory function of kisspeptin neurons on the secretion of GnRH." (PMID 34177811, 2021). "In both preclinical and clinical settings, testosterone treatment (TTh) of hypogonadism has shown beneficial effects on insulin sensitivity and visceral and liver fat accumulation." (PMID 32772323, 2021). "This view suggests a unifying mechanism for the distinct metabolic roles of androgens in the control of insulin action in men with hypogonadism and women with PCOS." (PMID 34987473, 2021). "On the other side, experimental animal models demonstrated that insulin exerts a stimulatory action on hypothalamic GnRH neurons, which results in gonadotropin release, therefore suggesting that IR associated with metabolic disorders might reduce gonadotropin secretion and promote hypogonadism." (PMID 31402895, 2019). "Several factors are involved in the pathogenesis of this form of hypogonadism, in particular, a role of estradiol, insulin, leptin, and other pro-inflammatory cytokines has been proposed." (PMID 31817436, 2019). "The current study demonstrates that insulin is a critical metabolic signal acting through astrocytes to permit reproductive competency via the GnRH network; astrocyte insulin signaling prevented hypogonadism and allowed normal fertility in adulthood." (PMID 30893295, 2019). "Our results suggest that a relatively mild hypogonadism is a frequent co-morbidity in insulin-resistant males." (PMID 29998109, 2018). "To analyse the metabolic alterations mainly related to decreased testosterone, we performed metabolomics investigations on the plasma of males with hypogonadism who showed normal insulin levels." (PMID 29844353, 2018). "Once compared with the analysis performed in IR male hypogonadism, these metabolite changes will allow us to better understand the role played by insulin when patients become insulin-resistant over time." (PMID 29844353, 2018). "Currently, the contribution of hypogonadism to inflammation and insulin resistance related mechanisms that regulate muscle mass loss during cancer cachexia is not well understood." (PMID 24285707, 2013).